PRAME (PRAME nuclear receptor transcriptional regulator)
Diseases named in the same sentence as PRAME in open-access papers (continued):
Sharing a sentence is not in itself a finding about the gene and the disease.
leukemia (36 papers, 2010 to 2025). A malignant (clonal) hematologic disorder, involving hematopoietic stem cells and characterized by the presence of primitive or atypical myeloid or lymphoid cells in the bone marrow and the blood. "Potentially leukemia-specific cell frequencies can be increased after stimulation of immune cells with leukemia-associated antigens (LAA) such as PRAME or WT1, respectively, with staphylococcal enterotoxin B (SEB) for healthy WB samples." (PMID 39000091, 2024). "More importantly, PRAME is also expressed on leukemic stem/progenitor cells (LSCs/LPCs), which are self-renewing cells that can produce many daughter blasts, a major cause of leukemia relapse." (PMID 38596687, 2024). "PRAME expression might induce caspase-independent cell death, inhibit cell proliferation, induce apoptosis, and cause cell cycle arrest in leukemia cells." (PMID 38596687, 2024). "In addition, PRAME-specific T cells also protect against LSCs/LPCs, which have been implicated in leukemia relapse." (PMID 38596687, 2024). "As PRAME promotes tumor growth via inhibition of retinoic acid induced differentiation and apoptosis, increased PRAME expression might cause accelerated leukemia cell growth and apoptosis resistance." (PMID 23940586, 2013). "It remains to be established whether loss of PRAME or ZNF280A genes are significant contributory factors in the pathogenesis of leukaemias and non-Hodgkin's lymphomas." (PMID 20799951, 2010). "Interestingly, the authors documented that the addition of nivolumab to CTL cultures for several days increased both specific T-cell responses against various leukemia-associated antigens, mainly PRAME, RHAMM and WT1, as well as T cell cytotoxic effects against primary AML blasts." (PMID 30783516, 2019). "Initially identified in cutaneous melanoma, where it was first characterized, PRAME has since been detected in numerous other tumor types, such as leukemia, neuroblastoma, non-small-cell lung cancer (NSCLC), breast cancer, ovarian cancer, and several sarcomas." (PMID 40868240, 2025). "For example, in leukaemia, particularly in acute myeloid leukaemia (AML), high PRAME expression has been associated with higher rates of disease relapse and is often used as a marker to monitor the minimal residual disease." (PMID 38338862, 2024). "The high expression of PRAME in leukemia cells and its silencing in normal hematopoietic cells have opened new possibilities for immunotherapy in AML." (PMID 38596687, 2024). "In a cohort of 28 pediatric AML patients, PRAME-positive patients (36%) exhibited significantly greater leukemia-free survival (LFS) than did PRAME-negative patients." (PMID 38596687, 2024). "PRAME is a classical cancer-testis antigen and is considered a highly attractive target in leukemias." (PMID 30897713, 2019). "Encouraging results for PRAME as a target for immunotherapy in leukemia were, however, reported by Rezvani and colleagues." (PMID 28638379, 2017). "Other attractive LAAs, including WT1 antigen, proteinase-3 peptide, PRAME, and RHAMM, which are self-antigens overexpressed in leukemia cells, can also serve as leukemia-associated targets for immune responses." (PMID 23394714, 2013). "Preferentially expressed antigen in melanoma (PRAME) has been described as a cancer-testis antigen and is associated with leukaemias and solid tumours." (PMID 23460923, 2013). "In PRAME-negative leukaemias the gene can be induced by demethylating agents, but little else is known regarding pathways that regulate PRAME expression." (PMID 23460923, 2013). "In summary, PRAME gene is a widely expressed leukemia gene that has been the focus of much scientific research in recent years." (PMID 23691459, 2012). "Compared with Wilm’s tumor (WT1) gene, PRAME gene, as another widely expressed leukemia gene, is more widely expressed in patients with normal karyotypes." (PMID 23691459, 2012).
leukemia (continued). "Studies abroad suggest that the PRAME gene is highly expressed in leukemic cells, and its expression levels are correlated with the relapse and the remission of leukemia." (PMID 23691459, 2012). "While PRAME mRNA was often significantly over-expressed in bone marrow samples from patients with newly diagnosed leukaemia (as compared with healthy donors), its expression level decreased to normal levels in patients who responded to treatment." (PMID 20799951, 2010). "Here we review the current knowledge of the structure/function of PRAME and its relevance in leukaemia." (PMID 20799951, 2010). "Leukemia-specific cells are specifically triggered immune cells that produce interferon gamma (IFNg), tumor necrosis factor α (TNFα) or initiate cells’ degranulation in the presence of leukemia-associated antigens (LAA) like WT1 or PRAME." (PMID 41226377, 2025). "Higher PRAME expression could indicate a higher tumor burden and the presence of more aberrant leukemia cells, while low PRAME expression could reflect a situation where leukemia cells can escape immune surveillance." (PMID 35328721, 2022). "Irrespective of the correlation between PRAME gene expression and all clinical parameters, the PRAME gene could be used as a potential marker for monitoring the malignancies with tumor-associated antigens (TAA) and leukemia-associated antigens (LAA)." (PMID 35788450, 2022). "Low levels of PRAME expression may reflect a situation where leukaemia cells are able to escape immune surveillance, while higher levels of PRAME could reflect a higher tumour load and/or the presence of more aberrant leukaemia cells." (PMID 30678059, 2019). "Similarly, the cancer‐germline gene PRAME is overexpressed in various cancer and leukemia types as well as in CML CD34+ cells." (PMID 29575763, 2018). "Therefore, PRAME has been recognized as a promising target for both active and adoptive anti-leukemia immunotherapy." (PMID 23940586, 2013). "Conflicting reports on leukaemia cells suggested that PRAME might induce caspase-independent cell death, or repress apoptosis-related genes to promote cell survival." (PMID 22912744, 2012). "The PRAME gene is also a promising component in the immunotherapy of leukemia." (PMID 23691459, 2012). "In the 34 leukemia patients, the expression rate of the PRAME gene was 38.2% (n=34)." (PMID 23691459, 2012). "Hence, this study investigated PRAME mRNA expression in leukemic patients and its relationship with clinical data such as white blood cell count, bone marrow blast count, immunophenotype of leukemia, and karyotype." (PMID 23691459, 2012). "Of those with active leukemia, 67% (6/9) were positive for BIRC5, 33% (3/9) for WT1, and 22% (2/9) for PRAME." (PMID 36248870, 2022). "Comparing the gene expression profiles between leukemia cells and normal human hematopoietic cells, only WT1 and PRAME expression was significantly higher in leukemia cells compared to normal human hematopoietic cells, in CML only PRAME." (PMID 31575892, 2019). "PRAME is highly expressed in leukemia cells and LPCs/LSCs but not in HSPCs, suggesting that it is a preferred target for AML treatment." (PMID 38596687, 2024). "PRAME is also expressed in other non-UM malignancies, including cutaneous melanoma, breast carcinoma, non-small cell lung cancer, and leukemia." (PMID 37626310, 2023). "Deg and InCyt assays were both conducted with/without stimulation with leukemia- associated antigens (LAA) (WT-1 and PRAME) for leukemic samples, or with/without stimulation with SEB for healthy samples (‘Stimulated’/‘Unstimulated’)." (PMID 37371569, 2023). "Adding leukemia-associated antigens (e.g., WT1 and PRAME) to cultures with/without the cultivation of cells can help to detect/enrich low frequencies of specific cells." (PMID 36613907, 2022).
leukemia (continued). "Greater frequency of PRAME-specific CD8+ T cells was evident in patients with AML, CML, and ALL than healthy controls, revealing the potential for developing PRAME as a target for immunotherapy in leukemia." (PMID 33503926, 2021). "Due to its highly tumor-specific expression pattern and more importantly, its well defined immunogenicity as demonstrated by specific killing of PRAME-expressing leukemia cells by PRAME antigen-specific CTL clones, PRAME has been recognized as a promising target for anti-leukemia immunotherapy." (PMID 23940586, 2013). "To determine if these tumor antigens could be simultaneously detected and discriminated for quantitation, we used cancer cell lines known to express the three TAA: hepatoblastoma (HEP3B), which expresses BIRC5; and K562, an immortalized leukemia line that expresses WT1 and PRAME." (PMID 36248870, 2022). "The hypothesis that the PRAME gene can be used in the monitoring of MRD is gradually being accepted, and the determination of this gene’s function is paving a promising way for the immunotherapy and gene-targeting treatment of leukemia." (PMID 23691459, 2012). "Because the PRAME gene is transcribed in leukemia cells and LSCs but not in normal BM or PB mononuclear cells, quantitative real-time PCR (qPCR) using PRAME-specific oligonucleotides may be a valuable tool for detecting leukemia cells." (PMID 38596687, 2024). "ddPCR simultaneously quantitated mRNA expression of WT1, PRAME, BIRC5, and ABL1 and the TAA/ABL1 blood ratio was measured in patients with and without active leukemia after HCT." (PMID 36248870, 2022). "Of the 19 patients with active disease, including those leukemias without elevated TAA/ABL1, the blood levels of WT1/ABL1, PRAME/ABL1, and BIRC5/ABL1 exceeded healthy donors (p<0.0001, p=0.0286, and p=0.0064 respectively)." (PMID 36248870, 2022). "Though PRAME expression is detected in a notable fraction of leukemia samples, PRAME specific CTL response is not detectable or at a very low level in most leukemia patients." (PMID 23940586, 2013).
breast carcinoma (34 papers, 2008 to 2025). "One such cancer class is breast cancer, where several studies have found increased PRAME expression to be associated with worse outcomes." (PMID 39451258, 2024). "A study analyzing Kaplan–Meier survival curves found that of 295 primary breast cancer lesions, PRAME expression was associated with decreased overall survival and increased rates of metastasis." (PMID 39451258, 2024). "We particularly focused on PRAME as its expression associates with EMT in breast cancer and laryngeal squamous cell carcinoma." (PMID 37173882, 2023). "Here, we show that PRAME tumour expression is associated with worse survival in the TCGA breast cancer cohort, particularly in immune‐unfavourable tumours." (PMID 34612587, 2021). "PRAME is implicated in the growth and metastasis of breast cancer, the hypomethylation of epithelial ovarian cancer, and the prognosis of nonsmall cell lung cancer." (PMID 32170852, 2020). "Next, we explored the association of PRAME with clinical outcome in the TCGA breast cancer dataset and found that PRAME expression correlated significantly with a shorter overall survival and to a lesser extent with a shorter disease-free survival." (PMID 30602372, 2019). "Staining of endogenous PRAME in MCF-7 breast cancer cells also revealed its association with Golgi-like structures." (PMID 23460923, 2013). "In conclusion, our analyses provide evidence for an association of high PRAME expression levels with poor clinical outcome of premenopausal breast cancer with increased rates of distant metastases and lower rates of overall survival." (PMID 18648365, 2008). "In the 295-breast cancer patient group, high PRAME expression levels were associated with poorly differentiated tumours and low PRAME expression with well-differentiated tumours (Kruskal–Wallis test: P=0.0005)." (PMID 18648365, 2008). "The presence of PRAME expression was associated with shortened disease-free survival and overall survival in all breast cancer cases." (PMID 18648365, 2008). "Notably, LMO1 and PRAME were strongly upregulated in the resistant cells, further highlighting their strong association with aggressive breast cancer phenotypes." (PMID 40076569, 2025). "An analysis of 295 breast cancer patients revealed that higher expression of PRAME was associated with poorly differentiated tumours, and PRAME expression was related to ER levels, as ER-negative patients had higher PRAME expression, whereas ER-positive patients had low PRAME expression." (PMID 34359776, 2021). "Moreover, PRAME expression has been associated with poor prognosis in solid cancers including breast cancer, sarcoma, head and neck cancer, medulloblastoma, uveal melanoma, and neuroblastoma." (PMID 31311081, 2019). "Because PRAME was not part of the 70-gene prognosis classifier, we have analysed the gene expression data set of the 295 breast cancer patients from our previous study for the expression levels of PRAME and found a remarkable association between PRAME expression and poor clinical outcome." (PMID 18648365, 2008). "One study examined the effects of PRAME, a cancer-testis antigen, overexpression in a breast cancer cell line." (PMID 40141328, 2025). "Another study used an HDAC inhibitor to bypass PRAME‐mediated retinoid resistance in breast cancer cells." (PMID 40101298, 2025). "In a breast cancer model, silencing PRAME in MDA-MB-468 cells was shown to enhance T-cell-mediated cytotoxicity and decrease the expression of immune checkpoint regulators." (PMID 40868240, 2025). "In summary, our data have confirmed broad expression of PRAME across a variety of solid tumor types, including cutaneous melanoma, endometrial, ovarian, lung, and breast cancers." (PMID 39659431, 2024). "PRAME expression is also considered an indicator of poor prognosis in several tumor types, including breast cancer, uveal melanoma, hepatocellular carcinoma, Hodgkin’s lymphoma, and neuroblastoma." (PMID 39659431, 2024).
breast carcinoma (continued). "In accordance, PRAME expression is significantly upregulated in breast cancer where it favors EMT and immunosuppression." (PMID 37173882, 2023). "The aim of this study was to detect the protein expression of the five CTAs (MAGE-A1, MAGE-A4, NY-ESO-1, PRAME, KK-LC-1) in breast cancer and find a possible universal target for breast cancer." (PMID 37610673, 2023). "Breast cancer patients with positive expression for either MAGE-A4 or PRAME have extended disease-free survival." (PMID 37610673, 2023). "PRAME expression was reported to be higher in basal-like breast cancer subtypes than other subtypes." (PMID 34359776, 2021). "We show that PRAME expression negatively correlated with overall survival in the TCGA breast cancer cohort, particularly in immune‐unfavourable tumours as defined by the Immunologic Constant of Rejection (ICR) score." (PMID 34612587, 2021). "For this purpose, we developed a breast cancer cell line model with stable overexpression of PRAME using the MDA‐MB‐468 basal‐like/triple negative breast cancer cell line." (PMID 34612587, 2021). "In the present study, we aimed to investigate the effect of PRAME overexpression in a breast cancer cell line on T cell activity in vitro and on the expression of immune‐related mediators." (PMID 34612587, 2021). "As such, PRAME harbors potential as a prognostic biomarker or therapeutic target for this specific subgroup of breast cancer patients." (PMID 30602372, 2019). "In the present study, we have evaluated the prognostic value of PRAME mRNA expression in 295 primary breast cancer biopsies." (PMID 18648365, 2008). "Recently, an association between PRAME expression and unfavourable disease outcome was shown in a study involving 103 breast cancer biopsies in which PRAME mRNA was detected in ∼53% of tumour specimens." (PMID 18648365, 2008). "The expression levels of PRAME mRNA in the primary breast cancer biopsies of 295 patients used in our previous study were analysed and matched to the clinical follow-up data." (PMID 18648365, 2008). "We have analysed PRAME gene expression in relation to clinical outcome for 295 primary breast cancer patients." (PMID 18648365, 2008). "In our study, we provide evidence that PRAME expression is a prognostic marker for metastasis-free interval and overall survival in primary breast cancer." (PMID 18648365, 2008). "PRAME was shown to be involved in this process in a breast cancer study." (PMID 39451258, 2024). "MAGE-A4, NY-ESO-1, PRAME and KK-LC-1 are overexpressed in breast cancer, especially in TNBC." (PMID 37610673, 2023). "Subsequently, PRAME was found to be expressed in several other cancers and high PRAME expression was demonstrated to be an independent prognostic marker for poor outcomes in breast cancer and neuroblastoma." (PMID 36980267, 2023). "Moreover, PRAME is also involved in other malignancies, such as non-small-cell lung cancer, esophageal cancer, ovarian carcinoma, and breast carcinoma." (PMID 36910848, 2023). "In silico analysis of the chimeric protein of PRAME in combination with the adjuvant FliC-D2D3 shows that this protein could be a great candidate for developing a new vaccine against breast cancer and stimulating cellular and humoral immunity." (PMID 36016136, 2022). "Thus, PRAME expression in our breast cancer cell line model can modulate the immune checkpoint expression on CD8+ T cells, most prominently in direct contact co‐cultures but also through indirect co‐culture." (PMID 34612587, 2021). "Using direct and indirect co‐culture models, we found that PRAME overexpressing MDA‐MB‐468 breast cancer cells inhibit T cell activation and cytolytic potential, which could be partly restored by silencing of PRAME." (PMID 34612587, 2021).